CXCR4 (C-X-C motif chemokine receptor 4)
Diseases named in the same sentence as CXCR4 in open-access papers (continued):
Sharing a sentence is not in itself a finding about the gene and the disease.
infection (continued). "In line with published data obtained with different infection systems, our data here show that the prototype CXCR4 antagonist AMD3100 can also efficiently inhibit the viral passage across the BeWo cell monolayer in contact with PBMCs infected by X4 or R5X4 HIV-1." (PMID 18377645, 2008). "Whilst blockade of cell surface receptors (CD4, CCR5 and CXCR4) within the mucosa may prevent localised infection of T cells and macrophages, viral uptake and dissemination by DC occurs through CD4 and MCLRs." (PMID 16882346, 2006). "This suggests that, as the infection progresses, ongoing treatment with the CXCR4 antagonist may help restore immune balance, facilitate inflammation resolution, support stem cell mobilization for lung repair, and reduce fibrosis, ultimately promoting tissue recovery and enhancing overall survival." (PMID 41451234, 2025). "In addition to exhibiting a diminished activation state, total CD8+ T cells from pregnant individuals that experienced breakthrough infection also expressed lower levels of tissue-homing receptors (CXCR4, CCR5, CCR6, and CD29); this effect was again primarily attributable to CD8+ Tcm cells." (PMID 40693463, 2025). "Interestingly, we found that the dual-tropic 89.6 virus caused higher levels of infection in the X4- and X4R5-DRSCs than in our R5-DRSCs, potentially indicating that the 89.6 virus infection was more efficient in utilizing the CXCR4 coreceptor relative to CCR5." (PMID 39998123, 2025). "Furthermore, we observed that the CXCR4 antagonist also enhanced neutrophil recruitment to the lungs without significantly impacting infection susceptibility in control mice." (PMID 41451234, 2025). "Besides the GC, CXCR4 regulation is also important to control extrafollicular response, that is, the T-independent immune response, which serves as the primary line of defense during infections." (PMID 38519141, 2024). "Lower dependence on virus entry receptors may also be responsible for the capacity of the X4 strains defined as T-tropic in cell-free infection assay to be efficiently transferred from infected T cells to MDMs through cell-cell fusion, while still using CXCR4 as coreceptor." (PMID 35622876, 2022). "Additionally, there are claims for a CD4-independent astrocyte infection pathway via cell-to-cell transfer from infected T cells to astrocytes, where actively budding virus Env protein binds to CXCR4 and facilitates fusion of the immature viral membrane and astrocyte membrane." (PMID 35975998, 2022). "Intriguingly, a study undertaken in neighboring Guinea Bissau reported 86% CXCR4 tropism in 111 CRF02_AG sequences from participants in late stage infection, suggesting that CXCR4 usage may occur more frequently in CRF02_AG, particularly as the infection progresses." (PMID 36680168, 2022). "Therefore, inflammation could also participate in the shift of the CXCR4/26 ratio in HHT patients with a history of severe infection, despite the significant time elapsed between the last episode of infection and the time of enrollment." (PMID 34906163, 2021). "However, it is also possible that during infection, other viral genes may modify or ablate the effects of US27 on CXCR4 signaling, particularly UL33 and UL78, which have been found to associate with CXCR4 and impair CXCL12-induced signaling outcomes." (PMID 28207860, 2017). "However, our results also evidence the long-term stability of viral reservoirs in naïve CD4+ T cells when the infection is driven by CXCR4-tropic viruses, as is the case of Pt-3, in whom TN cells account for >80 % of the total pool of infected cells at all the time points evaluated." (PMID 27484989, 2016). "Detection of R5×4 mixed infection in this study could be either the result of direct transmission of both variants, successive infections within a short timeframe, or a rapid switch from CCR5-using to CXCR4-using virus shortly after transmission." (PMID 26862570, 2016).
infection (continued). "As infection progresses, the virus evolves and may exhibit a coreceptor-switch to CXCR4." (PMID 26883082, 2016). "Furthermore, by demonstrating the susceptibility of TSCM to infection by C-HIV, our results highlight the potential for this subset of CD4+ T-cells to serve as a long-lived viral reservoir in individuals harboring CCR5- and CXCR4-using C-HIV viruses." (PMID 25387392, 2014). "Although R5 viruses typically persist into late stages of disease, CXCR4- or dual-tropic viruses emerge in approximately 50% of individuals infected with subtype B viruses, and coreceptor switching is also reported in subtype A, C, D, CRF01_AE, and CRF02_AG infections." (PMID 24676404, 2014). "Following long-term infection with virus derived from the pathogenic GL8 molecular clone of feline immunodeficiency virus (FIV), a range of viral variants emerged with distinct modes of interaction with the viral receptors CD134 and CXCR4, and sensitivities to neutralizing antibodies." (PMID 23372784, 2013). "Indeed, the authors demonstrated that inhibition of CXCR4-associated Gαi signaling with pertussis toxin inhibited HIV-mediated cofilin activation and actin dynamics, which resulted in a decrease of viral nuclear DNA as early as 2 h post infection." (PMID 22640593, 2012). "Susceptibility to infection by the human immunodeficiency virus type-1 (HIV-1), both in vitro and in vivo, requires the interaction between its envelope (Env) glycoprotein gp120 Env and the primary receptor (R), CD4, and Co-R, either CCR5 or CXCR4, members of the chemokine receptor family." (PMID 21284907, 2011). "Thus, infection in children established by R5broad viral variants with an envelope conformation that allows for a more efficient CCR5 use, determine detrimental effects similar to those known for CXCR4 using viruses." (PMID 21284900, 2011). "Given that CXCR4 expression alone does not confer susceptibility to infection with WT GL8, and that WT GL8 does not infect cells expressing CRD1 alone, these data suggest that the Fc-SU fusion proteins are in a distinct conformation that fails to mimic that found on native virions." (PMID 18721458, 2008). "Indeed, transfection of CD4-positive CCR5-negative cells with mutant CCR5 unable to transduce signals made such cells fully susceptible to infection with R5 HIV-1 (R5 viruses infect cells expressing CD4 and CCR5, while X4 viruses infect cells with CD4 and CXCR4)." (PMID 18808680, 2008). "CCR5 and CXCR4 have immunoregulatory functions that influence host defense and tissue inflammation, which can also affect HIV-1 replication and sustenance of infection." (PMID 41424846, 2026). "For example, Siglec-1 has been shown to catalyse productive infection, by stabilising interactions between HIV and both CCR5 and CXCR4." (PMID 40929143, 2025). "We also observed notable strain-specific differences in the phenotype with CXCR4-tropic, CCR5-tropic, and transmitted founder strains having different infection phenotypes in CPSF6 knock-out cells." (PMID 41385587, 2025). "Given the increase in CXCR4 cell surface expression in the CPSF6 knock-out cells, we next wanted to assess the impact of tropism on the observed infection phenotypes." (PMID 41385587, 2025). "At 5 days post-challenge, in the media only condition, CXCR4 and CYPA knock-out decreased infection while CPSF6 knock-out increased infection as expected." (PMID 41385587, 2025). "Inhibition of viral entry by AMD3100 or Maraviroc, which block the co-receptors CXCR4 and CCR548, respectively, together with VSV-G neutralizing antibodies completely abrogated infection and type I IFN induction." (PMID 41354661, 2025). "As expected, CXCR4 and CYPA knock-out strongly inhibited infection at days 2 and 5, including in the SQV-treated samples, confirming their role in the early phase of the lifecycle." (PMID 41385587, 2025).
infection (continued). "HIV-1LAI is a CXCR4 tropic strain unable to infect macrophages, whereas HIV-1NL4.3-BaL uses CCR5 as a co-receptor which is required for infection of macrophages." (PMID 40522834, 2025). "Although lectin receptors are predominantly involved in endocytic uptake and associated first-phase transfer, they can also concentrate the virus on the cell surface, leading to infection via CD4 and CCR5/CXCR4." (PMID 40929143, 2025). "Naive T cells express in addition to the CCR5 coreceptor also CXCR4, while memory T cells predominantly express CCR5, leading to infection by dual/X4-tropic and R5-tropic viruses, respectively." (PMID 39964317, 2025). "Meanwhile, we observed that certain biomarkers (SLC7A5, PDE4D, CXCR4, PER1, PIK3R1, HBA1, HBB) were elevated during the pre-infection phase (LTBI), while others (SOCS3, GZMK, HIS1H3B) were upregulated in the post-infection phase (ATB)." (PMID 40589756, 2025). "When mice were monitored up to 14 days post-infection, CXCR2 LOF mice also exhibited significantly reduced overall survival compared to control mice, and this reduction appeared to improve with CXCR4 antagonist treatment." (PMID 41451234, 2025). "Viruses that primarily use the CXCR4 coreceptor are termed X4-tropic, CCR5-biased viruses are X5-tropic, and dual-tropic viral strains also exist which can utilize either coreceptor for infection." (PMID 39998123, 2025). "HIV initiates infection by binding to the CD4 receptor and the chemokine co-receptors CCR5 or CXCR4 on the surface of host immune cells." (PMID 40699766, 2025). "HIV-1 initiates infection by binding to CD4 and then to either of the CCR5 or CXCR4 coreceptors, which are chemokine receptors that trigger Ca2+ fluxes." (PMID 41278678, 2025). "In patients with advanced infections, HIV-1 evolves to exploit CXCR4 which correlates with declining CD4+ T cell counts and accelerated progression to AIDS." (PMID 39638817, 2024). "Here, we find that knockout of JunB downmodulates CXCR4 expression in TZM-GFP cells, blocking HIV-1NL4-3 infection of these cells." (PMID 38835488, 2024). "As expected, CXCR4 and CYPA knock-out strongly repressed infection at days 2 and 5, with the SQV-treated samples confirming their role in the early phase of the lifecycle." (PMID 39678349, 2024). "Macrophages express the entry receptor CD4 and co-receptors CCR5 and CXCR4 which interact with the envelope protein of HIV-1 to facilitate entry and infection." (PMID 39119118, 2024). "After controlling for changes in surface marker expression frequency, the infection frequency of CCR5, α4β7, CCR5 + α4β7, CXCR4, and CD69 expressing CD4+ T cells remained greater in the EM of women following menopause." (PMID 39872519, 2024). "At 5 days post-challenge, in the media only condition, CXCR4 and CYPA knock-out decreased infection while CPSF6 increased infection as expected." (PMID 39678349, 2024). "In this study, we demonstrate that TIQ-15 is a novel tetrahydroisoquinolines-based CXCR4 antagonist that restricts Gαi-based SDF-1 signaling, thereby blocking HIV-1 entry and infection." (PMID 39146384, 2024). "We first infected each cell line with either of two CXCR4 (X4)-tropic HIV-1 strains, NL4-3 or IIIB, at a low multiplicities of infection (MOI 0.5) and maintained the cultures for 10 days to allow for multiple rounds of virus replication." (PMID 37676006, 2023). "HIS mice were infected intrathymically (direct injection of virus into the implant) with CXCR4-tropic (NL4-3) or mock (empty vector) HIV-1 and sacrificed at 5 or 9 weeks post-infection." (PMID 37762169, 2023). "CT also enhances the accumulation of CD4+ T cells that express the HIV co-receptors CXCR4 and CCR5 at the site of infection." (PMID 37766360, 2023). "CXCR4- and CCR5-tropic viruses induce different signaling pathways in cells at the time of infection." (PMID 38156317, 2023).
infection (continued). "Systemic inflammation and infection down-regulate CXCL12 transcripts and protein levels in vivo, whereas reduced CXCR4 function (CXCL12 receptor) in B-cell progenitors impairs B lymphopoiesis." (PMID 36717247, 2023). "We then analyzed the overlap of differentially expressed genes between the two sets of different donors infected with the CXCR4-tropic virus and between the CXCR4- and CCR5-tropic infections." (PMID 38156317, 2023). "Here, the current literature regarding CRISPR-mediated genome editing to render cells resistant to HIV (re)-infection by knocking out the co-receptors CCR5 and CXCR4 is summarized, and an outlook is provided regarding future (research) directions." (PMID 35892930, 2022). "U87-MG CD4/CXCR4 cells expressing wild-type MX2 or the S28D, T151D, T343D, or S28D/T151D mutants were challenged with these stocks, and infection was measured at 48 h." (PMID 35880880, 2022). "These cells express both the primary receptor of HIV (CD4) and its major co-receptors (CXCR4 and CCR5), permitting productive infection and replication of HIV in vitro." (PMID 35887383, 2022). "The analyses revealed that, compared to the H7N9 infection, the H9N2 infection induced an earlier induction of both CCR2 and CXCR4 transcripts, similar to that of CCL2 in the lung (data not shown)." (PMID 36034707, 2022). "Th17 cells participate in the dissemination of HIV following infection through their expression of mucosal migration receptors (CCR6, α4β7) and HIV co-receptors (CD4, α4β7, CCR5, and CXCR4) through different biological pathways." (PMID 35197986, 2022). "A CXCR4 KO was used as positive control, diminishing HIV-1 fusion and productive infection to background levels." (PMID 34949807, 2022). "Accordingly, studies using humanized mice observed infection of CD34+CD38+ progenitors by HIV-1 strains of all tropisms, including CCR5-tropic strains, albeit at much lower infection rates than by CXCR4-tropic or dual-tropic strains." (PMID 36230931, 2022). "This is likely due to the ability of CXCR4 utilizing NL4-3 to infect quiescent cells as compared to primary strains, which often require high levels of activation for infection." (PMID 35255110, 2022). "Early stages of infection are dominated by CCR5-tropic (R5) strains, whereas CXCR4-tropic (X4) strains are found predominantly in later stages of the disease." (PMID 36230931, 2022). "We were interested in testing a model where induction of an inflammatory state would increase infection of cells in the CNS, possibly by inducing expression of the entry receptor CD4 or coreceptors CCR5 or CXCR4." (PMID 35975998, 2022). "Th17 cell expression of mucosal migration receptors (CCR6 and α4β7), as well as HIV co-receptors (CD4, α4β7, CCR5, and CXCR4), participates in the remarkable capacity of these cells to disseminate HIV following initial infection." (PMID 35197986, 2022). "Low-level infection/transduction of HSPCs, including hematopoietic stem cells (HSCs) and multipotent progenitors (MPP), was observed, preferentially via CXCR4, but also via CCR5-mediated entry." (PMID 36230931, 2022). "This system facilitates investigation into interaction or interference of HIV-1 entry and infection via the co-receptors CCR5 and CXCR4 in the presence of Mycobacterium derived liposomes." (PMID 33669411, 2021). "This dimer was described to have potent anti-HIV-1 activity due to inhibition of infection with R5-tropic HIV-1 SF162 and CXCR4-tropic HIV-1 NL4-3 in TZM-bl cells, with an IC50 of 0.36 and 0.26 μM, respectively." (PMID 35126374, 2021). "To assess the role of entry vs. activation in our observed phenotypes, we compared infection rates by CCR5- and CXCR4-tropic HIV." (PMID 34899645, 2021). "During the generation of these latently infected cells, we observed differences in infection between AD8 and NL4-3, likely due to differences in infection efficiency between virus envelopes and/or less CCR5 expression than CXCR4 expression in this model." (PMID 33441346, 2021).
infection (continued). "Generally, during the early stages of infection, CCR5 is the main coreceptor, but as the infection progresses, gp120 binds to either CCR5 or CXCR4, or switches completely over to CXCR4." (PMID 34094761, 2021). "The second, CXCR4-utilizing T-tropic HIV, arises late in infection in about 50% of people living with HIV26." (PMID 33594125, 2021). "Intense research has already shown that EPI-X4 is able to interfere with the crosstalk of CXCR4 and CXCL12, inhibits infection with CXCR4-tropic HIV-1 strains, mobilizes hematopoietic stem cells and is able to suppress migration of leukemic cells in vitro." (PMID 33669329, 2021). "For these studies, we used the Jurkat LTR-GFP CCR5 + (JLTRG-R5) reporter cell line that expresses both HIV coreceptors—CCR5 and CXCR4—and produces GFP from the Tat-dependent viral LTR promoter upon infection with HIV." (PMID 33093566, 2020). "A proportion of EBV+ B cells are infectible by CXCR4-tropic HIV-1 in vitro and in vivo, and these HIV-infected B cells can transmit infection to previously virus-naïve humanized mice." (PMID 32576602, 2020). "We followed trans-infection through co-culture of iMDDCs with CD4+ T lymphocytes, in the presence of CXCR4-tropic replicative-competent HIV-1 expressing GFP." (PMID 32181159, 2020). "Most of the genes for chemokines/chemokine receptors (CCR2, CCR6, CCR7, CSF2RB, CX3CR1 and CXCR4) and cytokines/cytokines receptors (IL1R2, IL8, IL18, IL20RA and IL22RA2) were down-regulated after infection by vvIBDV at 3 dpi." (PMID 33110122, 2020). "We found that relatively few MAIT cells expressed CCR2, CCR4, CCR6, CXCR3, CXCR4, and CCR9 in the lungs, spleen, thymus, and LP both before and after infection." (PMID 32849637, 2020). "Activated primary CD4 T cells were infected with single-round CXCR4-tropic HIV-1 pseudoviruses, GFP− cells were sort-purified 4 days post infection, then each of the four genes were knocked down using pLKO.1-shRNA lentiviral vectors." (PMID 33270809, 2020). "Data from the infection experiments were further corroborated by the expression of Vpu-S52,56D in HeLa-CD4/CXCR4/CCR5 cells." (PMID 32127461, 2020). "First, we measured the activity of FD016 in inhibiting HIV-1 laboratory-adapted strains IIIB and Bal, using AMD3100, a CXCR4 antagonist, and Maraviroc, a CCR5 antagonist, as positive controls for inhibition of IIIB and Bal infection, respectively." (PMID 33569006, 2020). "Specifically, it was demonstrated that upon infection with VSV, all the subsets of mature neutrophils, including those that were CXCR4+, decreased in the bone marrow." (PMID 32882969, 2020). "We first infected the activated primary CD4 T cells with single-round CXCR4-tropic HIV-1 pseudoviruses, sorted GFP+ and GFP− cells 4 days post infection, and then conducted RT-qPCR in these two groups of cells." (PMID 33270809, 2020). "The PRE cells that survived infection despite the presence of YM155 expressed relatively high levels of NFAT, Tbet, and CXCR4." (PMID 32452381, 2020). "The R5-tropic virus strain of HIV-1 prevail using CCR5 as co-receptor for fusion with the cell in the early stage of infection, while the X4-tropic strain of HIV-1 utilizes CXCR4 as co-receptor." (PMID 31900106, 2020). "Regulation of CXCR4, DDX60 and NFKBIZ varied at different time points after infection of chicken lungs." (PMID 32381003, 2020). "For infection of MDM cultures, HIV viruses preferentially utilize CCR5 as a coreceptor, whereas viruses in T-cells use CXCR4." (PMID 31234437, 2019). "Further studies have shown that endogenous SDF-1 can competitively bind to CXCR4 on T cell membrane, thereby, inhibiting the entry of X4-tropic HIV-1 into T cells and protecting T cells from infection." (PMID 31540474, 2019). "We also compared DC-to-T cell transmission by T/F strains and laboratory-adapted CXCR4 and CCR5-tropic strains and found this mode of infection was efficient in amplifying infection by all the strains." (PMID 29293546, 2018).